MMP9 (matrix metallopeptidase 9)
Diseases named in the same sentence as MMP9 in open-access papers (continued):
Sharing a sentence is not in itself a finding about the gene and the disease.
lower respiratory tract infection (2 papers, 2012 to 2026). "Notably, MMP‐9 genes have been implicated in granulocyte responses during lower respiratory tract infection and respiratory syncytial virus (RSV) infectivity." (PMID 40952045, 2026).
lung neoplasm (2 papers, 2022 to 2023). A benign or malignant, primary or metastatic neoplasm involving the lungs. "However, we observed that patients with other lung neoplasms with the -1562CT genotype had a statistically higher MMP-9 concentration (x ̄ = 928.88 ng/mL) than patients with other lung neoplasms with the -1562CC genotype (x ̄ = 821.64 ng/mL, p = 0.023315)." (PMID 37445754, 2023). "Furthermore, we found the highest MMP-9 concentration in the -1562CT genotype in patients with other lung neoplasms (x ̄ = 928.88 ng/mL), and the lowest was once again observed in the non-smoking group (x ̄ = 452.62 ng/mL)." (PMID 37445754, 2023).
Lyme disease (2 papers, 2021). Lyme disease (named after the towns in the USA where the disease was first identified) is a bacterial infection caused by Borrelia burgdorferi. "Although we did not examine the CSF response in this study, a number of genes upregulated in the dura mater of infected mice have been reported to be elevated in the CSF of Lyme neuroborreliosis patients including cytokines/chemokines as well as the matrix metalloproteinases MMP3 and MMP9." (PMID 33524035, 2021).
Lymphatic Metastasis (2 papers, 2014 to 2021). Transfer of a neoplasm from its primary site to lymph nodes or to distant parts of the body by way of the lymphatic system. "Positive expression of VEGF and MMP-9 was correlated with lymphatic metastasis, the rates of which were both significantly higher in patients with lymphatic metastasis than those without it." (PMID 24829764, 2014). "Positive expression of MMP-9 was related with lymphatic metastasis, and the positive rate of MMP-9 expression was significantly higher in patients with lymphatic metastasis than those without it (χ2 = 18.27, P = 0.001)." (PMID 24829764, 2014). "Positive expression of VEGF and MMP-9 was correlated with lymphatic metastasis, and their positive expression rates were significantly higher in patients with lymphatic metastasis than those without it (VEGF: χ2 = 30.00; P = 0.001; MMP-9: χ2 = 18.27, P = 0.001)." (PMID 24829764, 2014).
lymphedema (2 papers, 2022 to 2024). Excess fluid collection in tissues, causing swelling. "At the sametime, such combinations of genotypes as VEGF-2578 CA:VEGF+936 TT: MMP9-1562 CT and VEGF-2578 CA:VEGF+936 TT: MMP2-1306 CC: MMP9-1562 CT were notfound among representatives of the group of healthy individualsand were identified exclusively among patients withprimary lymphedema." (PMID 39027126, 2024). "Thus, thefrequency of a combined genetic trait represented by a combinationof homozygous VEGF+936 CC: MMP3-1171 5A5A:MMP9-1562 CC among the patients with secondary lymphedema exceeds the frequency of a similar indicator in the controlgroup by more than 3 times (OR = 3.37; p = 0.0110)." (PMID 39027126, 2024). "However, the overall analysis showed that lymphedema increases the mRNA expression of type I and type III collagen, connective tissue growth factor (CTGF), ACTA‐2, FN‐1 and MMP‐9." (PMID 35652284, 2022).
lysosomal storage disorders (2 papers, 2023 to 2024). "The results show that the CeO-NPs induce PF, matrix metalloproteinase-9 (MMP-9), and tissue inhibitor of MMP, but SiO2 coating reduced CeO2-induced inflammation, phospholipidosis, and fibrosis." (PMID 37538179, 2023). "Elevated levels of MMP-2 and decreased levels of MMP-9 have also been observed in patients with mucopolysaccharidosis (MPS), suggesting that altered MMP expression may contribute to joint/bone abnormalities in other lysosomal storage disorders." (PMID 39590837, 2024).
macular edema (2 papers, 2012 to 2022). "The results suggest that MMP-9 is a proteomic biomarker of SRF accumulation, separate from macular edema." (PMID 22773904, 2012).
malignant fibrous histiocytoma (2 papers, 2023 to 2024). "As an illustration, MMP-9 is regarded as a significant prognostic factor for the survival of patients with malignant fibrous histiocytoma." (PMID 38342891, 2024).
melasma (2 papers, 2016 to 2025). "Basement membrane disruption caused by elevated levels of MMP-2 and MMP-9 facilitates the descent of melanocytes into dermis, which makes the treatment of melasma challenging." (PMID 27240341, 2016). "Our findings showed that the AOPT‐LTL treatment significantly increased the number of collagen fibers in the dermis and restored their arrangement by downregulating tryptase and MMP‐9, thereby curbing photoaging in guinea pigs with melasma." (PMID 40916844, 2025).
mental disorder (2 papers, 2022 to 2025). A disease that has its basis in the disruption of mental process. "The diagnostic value of MMP-9, S100-β, and GFAP in detectingpost-traumatic mental disorders is substantial, with a significant correlationobserved among the biomarkers." (PMID 39801405, 2025). "Serum levels of MMP-9, S100-β, and GFAP hold significant promise for thefuture diagnosis and management of post-traumatic mental disorders." (PMID 39801405, 2025). "Serum levels of MMP-9, S100-β, and GFAP were significantly elevated in the post-traumatic mental disorder group compared to the simple traumatic brain injury group (p < 0.001)." (PMID 39801405, 2025). "Spearman correlation analysis of serum MMP-9, S100-β,GFAP, and the incidence of post-traumatic mental disorders." (PMID 39801405, 2025). "Spearman correlation analysis showed that serum MMP-9, S100-β and GFAP were significantly positively correlated with the incidence of post-traumatic mental disorders (p < 0.001)." (PMID 39801405, 2025).
mucoepidermoid carcinoma (2 papers, 2014 to 2020). A carcinoma morphologically characterized the presence of cuboidal mucous cells, goblet-like mucous cells, squamoid cells, cystic changes, and a fibrotic stromal formation. "Our findings suggest that metallothionein plays an important role in the tumor invasion mechanism in mucoepidermoid carcinoma, through the regulation of proteins directly involved in this process, such as TGF-α, TNF-α and MMP-9." (PMID 31936364, 2020).
myasthenia gravis (2 papers, 2022 to 2024). Myasthenia gravis (MG) is a rare, clinically heterogeneous, autoimmune disorder of the neuromuscular junction characterized by fatigable weakness of voluntary muscles. "We evaluated the plasma levels of MMP-9 and MMP-2 and their tissue inhibitors TIMP-1 and TIMP-2 in a patients’ cohort with generalized myasthenia gravis (MG)." (PMID 36358365, 2022).
myelofibrosis (2 papers, 2014 to 2015). A partial or complete replacement of the bone marrow stroma by fibrous tissue. "Also the ratio of total TIMP1/MMP9 was significantly higher in patients with Myelofibrosis compared with controls (P = 0.0004)." (PMID 25906101, 2015). "In regard to MMP-9 this gene was not amongst the top-20 of the most up-regulated genes in PMF (MMP-9 was slightly upregulated in our myelofibrosis patients but not in ET and PV patients; data not shown)." (PMID 24454890, 2014).
neuronal tumor (2 papers, 2019 to 2022). Neuronal brain tumors are an uncommon group of central nervous system tumors that arise from cells with neuronal differentiation. "In summary, these results show that the transcription factor FOXO3 binds to the MMP-9 and MMP-13 promoters and elevates the MMP-13 enzymatic activity in neuronal tumor cells." (PMID 31861249, 2019). "Hence, we investigated the impact of FOXO3 on MMP-9 and MMP-13 promoter activity in the aggressive neuronal tumor cell lines IMR32 and SK-N-SH." (PMID 31861249, 2019).
ocular cicatricial pemphigoid (2 papers, 2020 to 2025). Ocular cicatricial pemphigoid (OCP) is a form of mucous membrane pemphigoid (a group of rare, chronic autoimmune disorders) that affects the eyes. "Here, we report the presence of ER stress at the ocular surface epithelia of patients with ocular cicatricial pemphigoid and demonstrate a role for the UPR in mediating the expression of MMP9 under proinflammatory conditions." (PMID 32042069, 2020).
odontogenic tumor (2 papers, 2016 to 2019). "Thus MMP-9 and collagen IV could be useful markers in assessing the degree of local aggressiveness of these odontogenic tumors, including the CEOTs." (PMID 27871286, 2016).
oncocytoma (2 papers, 2013 to 2014). "The mean values of MMP-2 and TIMP-1 were similar in the ccRCC and oncocytoma patients, whereas the mean values of MMP-9 were higher in the ccRCC patients compared with those of oncocytoma patients." (PMID 24520285, 2014). "In the pathological specimens, the mean serum values of MMP-2 and TIMP-1 and -2 were similar in the ccRCC and oncocytoma patients, whereas the value for MMP-9 was 2-fold higher in the ccRCC patients compared with the oncocytoma patients." (PMID 24520285, 2014). "MMP-9/NGAL complex in oncocytoma was positive in 25% (1/4) of samples (range, 18–145; 80±52), and was positive in 44% (7/16) of ccRCC specimens (range, 14–306; 122±80)." (PMID 23760084, 2013). "The results outlined in the present study indicate that the mean values of serum NGAL and MMP-9/NGAL complex are higher in ccRCC patients compared with oncocytoma patients." (PMID 23760084, 2013). "MMP-9 was detected in all specimens analyzed and with values of 203±111 (range, 82–327) and 411±174 (range, 168–730) observed in oncocytoma and ccRCC patients, respectively." (PMID 23760084, 2013). "By gelatin zymography, we have previously demonstrated that the most abundant serum lytic activity was at 92 kDa (MMP-9) and that MMP-9 activity was slightly enhanced in sera from ccRCC patients compared with oncocytoma patients." (PMID 23760084, 2013). "MMP-9/NGAL complex was undetectable in all urine samples analyzed from oncocytoma and ccRCC patients." (PMID 23760084, 2013). "Urinary MMP-9 was detected in only one oncocytoma specimen with a value of 8.13 ng/ml, and in 67% (6/9) of ccRCC patients (range, 0.55–22.8; 4.38±7.4)." (PMID 23760084, 2013). "MMP-9 was detected in all the specimens analyzed, with mean values of 203±111 ng/ml (range, 82–327 ng/ml) and 411±174 ng/ml (range, 168–730 ng/ml) observed in the oncocytoma and ccRCC patients, respectively." (PMID 24520285, 2014). "In addition, the serum MMP-9 level was 2-fold higher in the patients with ccRCC compared with those with oncocytoma." (PMID 24520285, 2014). "Using a zymography technique, our previous study showed that MMP-9 is enhanced in the sera from ccRCC patients compared with that from oncocytoma patients, and that the most abundant lytic activity was at 92 kDa (MMP-9), whereas MMP-2 was present in reduced quantities." (PMID 24520285, 2014). "In sera, MMP-9 was enhanced in ccRCC patients compared with oncocytoma patients." (PMID 23760084, 2013). "In addition, the serum MMP-9 level is 2-fold higher in ccRCC compared with oncocytoma specimens." (PMID 23760084, 2013). "By ELISA, we detected no MMP-9/NGAL in urine specimens of oncocytoma and ccRCC patients and only in 10% of urine specimens from healthy individuals." (PMID 23760084, 2013).
oral disease (2 papers, 2024 to 2026). "The most important salivary inflammatory biomarkers linked to oral disorders include matrix metalloproteinases (MMP-8 and MMP-9), tissue inhibitors of metalloproteinase, interleukins (IL-1, IL-6, and IL-8), and tumor necrosis factor (TNF-α)." (PMID 38535833, 2024).
otitis media (2 papers, 2012 to 2015). Inflammation of the anatomical structures of the middle ear, which is most often caused by an infectious process. "As it relates to S. aureus colonization, a role for MMP9 has yet to be described; however, staphylococcal lipoteichoic acid has been shown to increase production of MMP9 in middle ear epithelial cells suggesting that increased MMP9 levels could be involved in progression of otitis media." (PMID 26569114, 2015).
ovarian serous carcinoma (2 papers, 2023 to 2025). "Decreased SERPINA5 expression was correlated with downstream activation of MMP9 in ovarian serous carcinomas." (PMID 40698088, 2025). "Furthermore, a significant increase in the expression levels of MMP7, MMP9, and MUC16 genes was observed in the serous ovarian carcinoma groups (LGSOC and HGSOC) when compared to the BSC group." (PMID 37569592, 2023).
plaque psoriasis (2 papers, 2006 to 2021). "An increase in immunolabeling of metalloproteinase-9 (MMP9) in the epidermis of the psoriasis plaque can be seen compared to the Non-affected and Control Groups." (PMID 34715781, 2021).
pneumonitis (2 papers, 2020 to 2021). An inflammatory process affecting the lung parenchyma. "Both myeloperoxidase (MPO) and matrix metallopeptidase-9 (MMP-9), products of activated neutrophils, and lactate dehydrogenase (LDH), a surrogate marker of tissue injury, were markedly increased in the BAL fluid of patients with pneumonitis." (PMID 33584685, 2020).
postmenopausal osteoporosis (2 papers, 2020 to 2021). Metabolic disorder associated with fractures of the femoral neck, vertebrae, and distal forearm. "During this study, the enzyme activity of serum MMP-9, TIMP-1, as well as MMP-9/TIMP-1 ratio were observed in patients with postmenopausal osteoporosis, before and after prescribing to a 12-week exercise program." (PMID 32071923, 2020). "Thus the demonstration of MMP-9 and TIMP-1 in serum of female patients with postmenopausal osteoporosis provides information about bone turnover and its changing depending on exercise therapy." (PMID 32071923, 2020). "We reported decreased enzyme activity of MMP-9, as well as increased TIMP-1 in the serum of female patients with postmenopausal osteoporosis, who had been involved in a 12-week exercise program, compared with those who have not got any physical activity treatment." (PMID 32071923, 2020). "In our study, we have tried to evaluate the response of enzyme activity of serum MMP-9 and TIMP-1 on appropriate treatment in postmenopausal osteoporosis, which must include pharmacological and nonpharmacological therapy." (PMID 32071923, 2020).
Primary glaucoma (2 papers, 2018 to 2021). "A genetic variant at the promoter region in the MMP9 gene (-1562C>T) has a putative role in regulating its transcription rate and hence can affect genetic predisposition to primary glaucoma." (PMID 29432439, 2018). "Current findings suggest significant association of MMP9 -1562C>T polymorphism with primary glaucoma in the targeted north Indian population and warrant further replication of the findings in other populations." (PMID 29432439, 2018). "The present study therefore aims to assess whether -1562C>T polymorphism in the MMP9 gene promoter is associated with primary glaucoma in a north Indian population since the polymorphism has not been investigated in the targeted population, more so in any Indian population." (PMID 29432439, 2018).
Primary immunodeficiency (2 papers, 2025). "MMP9 participated in antigen processing and presentation, complement and coagulation cascades, primary immunodeficiency, ribosome, RIG-I-like receptor signaling pathway, and Toll-like receptor signaling pathway." (PMID 40574839, 2025).
renal hypertension (2 papers, 2016). Hypertension caused by the kidney's hormonal response to narrowing or occlusion of the renal arteries. "Seven of them (Agtr1a, Fn1, Gja1, Lama2, Mmp2, Mmp9, Nos3) are known as being associated with renal hypertension." (PMID 28105926, 2016). "Six of these genes (Ace, Cyp2j4, Gja1, Mmp9, Ppara, and Ren) were described as genes associated with renal hypertension." (PMID 26821914, 2016). "The changes in expression of DEGs associated with renal hypertension (Agtr1a, Fn1, Gja1, Lama2, Mmp2, Mmp9, Nos3) may also be suggested to have a significant impact on disease development in ISIAH rats." (PMID 28105926, 2016).
renovascular hypertension (2 papers, 2014 to 2024). High blood pressure secondary to renal artery stenosis. "In cardiac inflammation caused by renovascular hypertension, CA may interact with TNF α, IL-17, COX2, and MMP9 to affect their protein stability and reduce their expressions, thus playing a role in improving inflammation." (PMID 39337549, 2024).
respiratory syncytial virus infection (2 papers, 2020 to 2022). "In this study, high doses of AZM were safe, reduced endotracheal MMP-9 levels in patients receiving mechanical ventilation, and potentially improved outcomes in critically ill children with respiratory syncytial virus infections." (PMID 32324238, 2020). "Previous studies have observed that type I IFNs inhibit TNF-α-dependent MMP-9 activation in tumour cell lines, and IFN therapy can suppress MMP expression in tumour models and during respiratory syncytial virus infection in mice." (PMID 35512020, 2022).
RSV bronchiolitis (2 papers, 2015 to 2020). "We recently reported higher MMP-9 activity in lung secretions of intubated children with RSV bronchiolitis when compared to controls, and found a positive correlation between early elevation of MMP-9 and disease severity." (PMID 26264019, 2015). "We demonstrated that RSV infection was a potent stimulus of MMP-9 expression and release from human airway epithelial cells, that reduced MMP-9 expression resulted in decreased viral titer, and that these observations extended to an in vivo mouse model of RSV bronchiolitis." (PMID 26264019, 2015). "Because of the direct relationship between MMP-9 and RSV disease, coupled with its potential as a therapeutic target, we tested the impact of MMP-9 expression first in an in vitro, then in vivo animal model of RSV bronchiolitis." (PMID 26264019, 2015). "As MMP-9 levels are significantly elevated in RSV-infected children, selective inhibition of MMP-9 activity may be of significant benefit for the treatment of RSV bronchiolitis." (PMID 32726921, 2020).
salivary gland tumor (2 papers, 2014 to 2020). "The aim of our study was to determine the concentration of serum MMP-9 in normal subjects and in the patients with salivary gland tumor." (PMID 25469360, 2014). "MMP9 expression in the salivary gland tissue was evaluated but their serum level in the salivary gland tumors was not studied." (PMID 25469360, 2014).
schistosomiasis (2 papers, 2011 to 2012). An infectious disease caused by parasitic trematodes of the genus Schistosoma that colonize human blood vessels and release eggs that can cause granulomatous reactions leading to acute (swimmer's itch or acute schistosomiasis syndrome) or chronic disease. "In vitro, we demonstrated that CXCL9 and CXCL10 inhibited the expression of collagen, TGF-β and TIMP1 of hepatic non-parenchymal cells of mice infected with S. japonicum, while increased the gene expression of MMP9, suggesting that they played an anti-fibrosis role in the liver of schistosomiasis." (PMID 22905138, 2012).